WNT10B (Wnt family member 10B)
Diseases named in the same sentence as WNT10B in open-access papers (continued):
Sharing a sentence is not in itself a finding about the gene and the disease.
liver fibrosis (3 papers, 2016 to 2023). "WNT pathway genes (including Wnt10b) are upregulated in activated hepatic stellate cells leading to liver fibrosis." (PMID 36814601, 2023). "MSCs reduce liver fibrosis, and the treatment of liver fibrosis in rats with exosomes from MSCs decreased Wnt10b expression." (PMID 36814601, 2023). "In the current study, the Hh-related genes, including Bmp4, Gas1, Gli3, Hhip, Ihh, Prkacb, Stk36, Wnt6, Wnt10b, Wnt9a and Wnt11, were dysregulated in our murine model of CCl4-induced liver fibrosis." (PMID 27322257, 2016). "In addition to WNT10B, other WNTs, including WNT1, WNT3/3A, WNT4A, and WNT5A, are implicated in liver fibrosis." (PMID 36814601, 2023). "Both hBM-MSCs and hBM-MSCs-Ex treatment significantly inhibited the expression of PPARγ, Wnt3a, Wnt10b, β-catenin, WISP1, Cyclin D1, α-SMA, and Collagen I in both HSCs and liver fibrosis tissues (p < 0.005, p < 0.001)." (PMID 30885249, 2019). "In addition, we found that hBM-MSCs-Ex inhibited the expression of Wnt/β-catenin pathway components (PPARγ, Wnt3a, Wnt10b, β-catenin, WISP1, Cyclin D1), α-SMA, and Collagen I, in both HSCs and liver fibrosis tissue." (PMID 30885249, 2019).
pulmonary fibrosis (3 papers, 2011 to 2025). Chronic progressive interstitial lung disorder characterized by the replacement of the lung tissue by connective tissue, leading to progressive dyspnea, respiratory failure, or right heart failure. "Only one paper has investigated WNT10B in the progression of lung cancer, and further work should be carried out to elucidate the actions of WNT10B in normal lung cells, lung fibrosis, and lung cancer." (PMID 36814601, 2023). "Conversely, the reduction of WNT10B by siRNA decreased mesenchymal markers and pulmonary fibrosis." (PMID 36814601, 2023). "Konigshoff and colleagues confirmed the up-regulation of WNT1, WNT7B and WNT10B, FZD2, FZD3, β-catenin, and LEF1 expression in the lungs of individuals with idiopathic pulmonary fibrosis compared to transplant donor lung." (PMID 21490961, 2011).
systemic sclerosis (3 papers, 2019 to 2024). A chronic disorder, possibly autoimmune, marked by excessive production of collagen which results in hardening and thickening of body tissues. "In the skin, WNT10B has been reported to induce hair follicle regeneration and has been linked to systemic sclerosis." (PMID 31089877, 2019). "We and others have demonstrated that canonical WNT ligands, such as WNT1 and WNT10B, are overexpressed in patients with Systemic Sclerosis (SSc) and in other fibrotic diseases." (PMID 38747285, 2024). "In addition, in the past decade, further work in systemic sclerosis (SSc) and fibrosis in additional tissues [heart (see Section 12), lungs, liver, and penis] demonstrate a function for WNT10B, specifically in fibrosis." (PMID 36814601, 2023).
asthma (2 papers, 2019 to 2023). "Another recent study suggested that Wnt10b regulates type 2 inflammation and the activation of Th2 cells, since Wnt10b deficiency was found to exacerbate house dust mite-induced asthma in mice." (PMID 31616443, 2019).
cholangiocarcinoma (2 papers, 2012 to 2023). A carcinoma that arises from the intrahepatic biliary tree (intrahepatic cholangiocarcinoma) or from the junction, or adjacent to the junction, of the right and left hepatic ducts (hilar cholangiocarcinoma). "In the first study of WNT10B in cholangiocarcinoma (biliary tract cancer), WNT10B was inhibited by miR-370, which in turn is inhibited by IL6." (PMID 36814601, 2023). "Therefore, although the mechanism of WNT10B in cholangiocarcinoma is unknown, WNT10B reduction appears to correlate with less tumor proliferation." (PMID 36814601, 2023). "While the function of WNT10B in cholangiocarcinoma was not described, miR-370 overexpression reduced proliferation and was downregulated in cholangiocarcinoma versus normal tissue." (PMID 36814601, 2023).
diabetes (2 papers, 2022 to 2023). "The probiotic Lactobacillus reuteri (L. reuteri) also prevented diabetes-induced bone loss while increasing Wnt10b expression in a total bone analysis." (PMID 36814601, 2023). "The suppression of Wnt10b in bone after glucocorticoid treatment was restored by L. reuteri, as in the diabetes model described previously." (PMID 36814601, 2023). "Overexpression of Wnt10b in osteoblasts via the osteocalcin promoter prevented diabetes-induced bone loss and marrow adiposity but did not affect blood glucose levels." (PMID 36814601, 2023). "To further vertify the connection between Wnt10b expression and DM, we searched in public Gene Expression Omnibus (GEO) database and found a previous study (GSE26168) that analyze the blood samples from male pre-diabetes and T2DM patients." (PMID 36091442, 2022).
idiopathic pulmonary fibrosis (2 papers, 2011 to 2021). Idiopathic pulmonary fibrosis (IPF) is a nonneoplastic pulmonary disease that is characterized by the formation of scar tissue within the lungs in the absence of any known cause. "Overexpression of Wnt1 and Wnt10b proteins has been observed in human samples from SS, idiopathic pulmonary fibrosis (IPF), and liver cirrhosis." (PMID 34685439, 2021).
leukaemia (2 papers, 2016 to 2023). "This expansion of hematopoietic precursors at the expense of differentiated cell types, such as neutrophils, resembles pre-leukemic HSC expansion suggesting a function for wnt10b in leukemia generation." (PMID 36814601, 2023).
neuroblastoma (2 papers, 2012 to 2023). Neuroblastoma (NB) is the most common solid, extracranial childhood tumor. "Other studies identified WNT10B overexpression in ovarian endometrioid carcinoma, in approximately 58% of B-cell progenitor acute lymphoblastic leukemia and in neuroblastomas." (PMID 23110045, 2012). "Isotretinoin-mediated neuroblastoma cell differentiation is orchestrated by targeting MYCN, cyclin D3, and Wnt10B." (PMID 38249515, 2023).
osteoarthritis (2 papers, 2021 to 2023). A noninflammatory degenerative joint disease occurring chiefly in older persons, characterized by degeneration of the articular cartilage, hypertrophy of bone at the margins and changes in the synovial membrane. "Several of these SNVs, rs3771501 (TGFA), rs3993110 (TEAD1/DKK3), rs72979233 (CHRDL2), and rs7967762 (PFKM/WNT10B), are associated with multiple osteoarthritis joint sites." (PMID 34450027, 2021). "Wnt family member 1 (WNT1) and wnt family member 10B (WNT10B) are involved in the Wnt signaling pathway, which has an established role in osteoarthritis pathogenesis." (PMID 34450027, 2021).
periodontitis (2 papers, 2025). An acute or chronic inflammatory process that affects the tissues that surround and support the teeth. "For instance, gingival tissues from patients with stage 3 periodontitis display higher Wnt3a, Wnt10b and nuclear β-catenin immunohistochemical staining, indicating the participation of the Wnt/β-catenin in periodontitis." (PMID 40421179, 2025). "In the upregulated Wnt/β-catenin Signaling pathway, Wnt Family Member 10B (Wnt10B) was upregulated in periodontitis (Log2FC>1.5)." (PMID 41124422, 2025). "The Periodontitis group showed increased nuclear Wnt10B expression in the epithelium (mainly in the suprabasal cell layer) and connective tissue compared to the Healthy group." (PMID 41124422, 2025).
psoriasis (2 papers, 2019 to 2023). An autoimmune condition characterized by red, well-delineated plaques with silvery scales that are usually on the extensor surfaces and scalp. "The role of WNT10B in the skin is further elucidated by examining skin pathologies, such as SSc and psoriasis." (PMID 36814601, 2023). "In this study, we also analyzed SNPs in WNT7B, WNT10B, WNT16 and TFC7L2 to investigate a possible association with psoriasis." (PMID 31089877, 2019). "Associations between single nucleotide polymorphisms for WNT7B, WNT10B, WNT16 and TCF7L2 genes and psoriasis were tested." (PMID 31089877, 2019). "The gene expression of WNT10B and WNT7B increases after treatment with narrowband UV, which is a therapy for psoriasis." (PMID 36814601, 2023). "Treatment with nbUVB induced a significant increase of WNT7B (p < 0.01), WNT10B (p < 0.001) and TCF7L2 (p < 0.01) gene expression in lesional skin of patients with psoriasis." (PMID 31089877, 2019). "This study shows for the first time significant UVB induced upregulation of WNT7B, WNT10B and TCF7L2 in patients with psoriasis and suggests a potential role of these genes in psoriasis pathogenesis." (PMID 31089877, 2019). "Samples from the lesional skin of psoriasis patients show significantly decreased WNT10B gene expression compared to the non-lesional skin of patients and skin from healthy individuals." (PMID 36814601, 2023). "The functional contribution of WNT signaling to the pathophysiology of psoriasis needs to be studied further, but it can be speculated that WNT7B, WNT10B, TCF7L2 and WNT16 contribute to the pathogenesis of psoriasis." (PMID 31089877, 2019). "Our IHC results on WNT10B protein levels in the skin suggest a slightly more prominent protein expression in controls compared to lesional and non-lesional skin of patients with psoriasis." (PMID 31089877, 2019). "Levels of WNT7B, WNT10B, WNT16 and TCF7L2 gene expression in peripheral blood samples of patients with psoriasis were not significantly different compared to healthy individuals." (PMID 31089877, 2019). "Gene expression analysis revealed significantly decreased WNT7B, WNT10B and TCF7L2 expression levels in lesional skin compared to non-lesional skin of patients with psoriasis (p < 0.001)." (PMID 31089877, 2019). "The aim of this study was to describe the expression of WNT7B, WNT10B, WNT16 and TCF7L2 in lesional and non-lesional skin and in whole blood of patients with psoriasis compared to healthy individuals and to investigate if SNPs in these genes can be correlated to psoriasis." (PMID 31089877, 2019).
triple-negative breast carcinoma (2 papers, 2013 to 2017). An invasive breast carcinoma which is negative for expression of estrogen receptor (ER), progesterone receptor (PR), and human epidermal growth factor receptor 2 (HER2). "We have linked HMGA2 regulation by Wnt10b/β-catenin signalling from the embryonic mammary gland anlagen to triple-negative breast cancer." (PMID 23307470, 2013). "We have validated the specificity of the WNT10B antibody utilizing transgenic MMTV-Wnt10b-IRES-LacZ-derived tumours and cell lines, human triple negative breast cancer cell lines and Wnt10b-knockout embryos (E.14.5)." (PMID 23307470, 2013).
allergic asthma (1 paper, 2025). A asthma with a basis in a pathological type I hypersensitivity reaction. "Wnt10b deficiency mice of allergic asthma results in enhanced memory T cell activation, increased Th2 polarization as evidenced by elevated IL-4 and IL-13 concentrations, and recombinant Wnt10b increases the percentage of naïve CD4+T and CD8+T cells in vitro, thereby mitigating allergic asthma." (PMID 40433386, 2025).
alopecia (1 paper, 2025). Hair loss usually from the scalp. "Western blotting analysis demonstrated that in the model group, sodium hydrosulfide‐induced alopecia led to significant downregulation of Wnt10b and β‐catenin, and upregulation of GSK‐3β." (PMID 40678337, 2025).
Alzheimer disease (1 paper, 2021). A progressive, neurodegenerative disease characterized by loss of function and death of nerve cells in several areas of the brain leading to loss of cognitive function such as memory and language. "It is interesting to note that Wnt10b expression was found to be down-regulated in the aging brain and in Alzheimer disease brains, conditions that are known to be associated with aneuploidy." (PMID 33257473, 2021).
brain cancer (1 paper, 2023). A primary or metastatic malignant neoplasm affecting the brain. "Future studies will be needed to better understand the mechanistic role of WNT10B to determine if WNT10B is an oncogene or tumor suppressor in brain cancer." (PMID 36814601, 2023).
cerebral infarction (1 paper, 2012). An ischemic condition of the brain, producing a persistent focal neurological deficit in the area of distribution of the cerebral arteries. "In this study, we analyzed the distribution of WNT10B polymorphism in elderly Korean subjects with cerebral infarction (CI) and Yin Deficiency pattern and Non-Yin Deficiency pattern." (PMID 22927882, 2012).
cognitive deficit (1 paper, 2025). "Specifically, microglia-derived EVs were found to carry miR-152-3p, which inhibits WNT10b signaling, disrupts neurogenesis in the DG, and contributes to post-SCI cognitive deficits." (PMID 40756360, 2025). "We identified WNT10b as a target gene regulated by miR-152-3p and confirmed that the activation of WNT pathway in hippocampal NSCs could rescue the cognitive deficit following SCI." (PMID 40756360, 2025).
colon adenocarcinoma (1 paper, 2023). "A bioinformatics study in patients with colon adenocarcinoma demonstrated that high WNT10B expression was an independent predictor of worse overall survival in patients." (PMID 36814601, 2023). "However, the role of WNT10B in colon adenocarcinoma is not well documented." (PMID 36814601, 2023).
Genetic obesity (1 paper, 2016). "Those authors also crossed FABP4-Wnt10b and lethal yellow agouti (Ay) mice and showed that Wnt10b protected against genetic obesity in mice due to the ectopic expression of agouti (Ay)." (PMID 27313625, 2016).
Glucose intolerance (1 paper, 2019). Glucose intolerance (GI) can be defined as dysglycemia that comprises both prediabetes and diabetes. "It has been proposed that transgenic overexpression of Wnt10b in adipose tissue reduces epididymal and peri-renal fat depots by β-catenin stabilization and improves glucose intolerance." (PMID 31470850, 2019).
hip fracture (1 paper, 2016). Traumatic or pathological injury to the hip in which the continuity of either the femoral head, femoral neck, intertrochanteric or subtrochanteric regions is broken. "Furthermore, proximal femur bone samples from osteoporotic women with hip fractures exhibit decreased Wnt10b expression, providing evidence for a relationship between Wnt10b expression, the maintenance of osteoblastic differentiation and bone strength." (PMID 27536268, 2016).
human papillomavirus infection (1 paper, 2023). "Another significant SNP, 27:5603116, was in an intronic region of the WNT10B gene, which is involved in the pathways ‘human papillomavirus infection’, ‘proteoglycans in cancer’, and ‘pathways in cancer’." (PMID 37756103, 2023).
ischemic cardiomyopathy (1 paper, 2023). Ischemic cardiomyopathy is a cardiomyopathy in which a weakness in the muscle of the heart due to inadequate oxygen delivery to the myocardium with coronary artery disease being the most common cause. "WNT10B is expressed in the intercalated discs of normal cardiomyocytes, and in ischemic cardiomyopathy patients, WNT10B accumulates along the lateral borders of cardiomyocytes." (PMID 36814601, 2023).
lung carcinoma (1 paper, 2023). "Overall, this study concluded that circTUBGPC3 promotes lung cancer progression by inhibiting miR-885-3p, thus allowing for the overexpression of WNT10B." (PMID 36814601, 2023).
lymph node metastasis (1 paper, 2021). "The elevated expression of wnt10b was associated with gender (P = 0.002) and lymph node metastasis (P = 0.023)." (PMID 34872582, 2021).
lymphoma (1 paper, 2023). A malignant (clonal) proliferation of B- lymphocytes or T- lymphocytes which involves the lymph nodes, bone marrow and/or extranodal sites. "For the significant SNP in WNT10B, there was a higher frequency of lymphoma cases (42%) that were homozygous for the minor allele than carriers (26%) and controls (5%)." (PMID 37756103, 2023).
metastatic cancers (1 paper, 2023). A carcinoma which has spread from the original site of growth to another anatomic site. "WNT10B has a more complex association, being highly expressed in the neonatal prostate, low in adults, and then high in metastatic cancers and in cell lines with a high metastatic potential." (PMID 37373067, 2023).
metastatic disease (1 paper, 2017). "We have previously shown that TNBCs are active for oncogenic Wnt10b/β-catenin signaling and that WNT10B ligand and its downstream target HMGA2 are predictive of poorer outcomes and are strongly associated with chemoresistant TNBC metastatic disease." (PMID 29281678, 2017).
metastatic prostate carcinoma (1 paper, 2023). A carcinoma that arises from the prostate gland and has spread to other anatomic sites. "WNT7B, WNT9A and WNT10B were all increased in metastatic prostate cancer, compared to the normal prostate." (PMID 37373067, 2023). "Indeed, in the GEO datasets presented here (GSE6919 and GDS1439), WNT7B, WNT9A and WNT10B were all increased in metastatic prostate cancer, where PHB levels were reduced." (PMID 37373067, 2023).
myocardial infarction (1 paper, 2023). Gross necrosis of the myocardium, as a result of interruption of the blood supply to the area, as in coronary thrombosis. "Recent investigations into molecular mitigation of ischemic cardiotoxicity observed that Wnt10b is strongly and transiently induced after myocardial infarction (MI) during the granulation tissue formation phase of cardiac repair, where neovascularization and fibrosis occur." (PMID 37856516, 2023).
oral squamous cell carcinoma (1 paper, 2023). "miR-148a also inhibits WNT10B in oral squamous cell carcinoma (OSCC)." (PMID 36814601, 2023).
osteogenesis imperfecta (1 paper, 2021). Osteogenesis imperfecta (OI) comprises a heterogeneous group of genetic disorders characterized by increased bone fragility, low bone mass, and susceptibility to bone fractures with variable severity. "Mutations in WNT10B have been linked to limb defects and dental abnormalities, and mutations in WNT1 are associated with osteogenesis imperfecta." (PMID 34450027, 2021).
osteosclerosis (1 paper, 2022). Abnormally high bone density. "Mature osteoclasts can reduce the Wnt signaling pathway inhibitor osteosclerosis protein expression and through the secretion of Wnt10b and BMP6 promoting osteoclast areas of osteoblast differentiation and bone formation." (PMID 35794997, 2022).
polyp (1 paper, 2024). A usually exophytic mass attached to the underlying tissue by a broad base or a thin stalk. "DKK1 and DKKL1 showed a significant upregulation in polyp specimens, while WNT10B, GREM1, RSPO3, SFRP5, and GPC3 showed a downward trend." (PMID 38473810, 2024). "Significant dysregulation of the expression of critical genes, including DKK1, GPC3, BMP7, FGF17, and WNT10B, was observed in the PPI network; this dysregulation could potentially be associated with the proliferation of polyp tissues." (PMID 38473810, 2024).
postmenopausal osteoporosis (1 paper, 2020). Metabolic disorder associated with fractures of the femoral neck, vertebrae, and distal forearm. "PTH is a bone anabolic agent and effective treatment for postmenopausal osteoporosis, maybe by its effect of increase Wnt10b production in osteoblasts." (PMID 33013696, 2020). "Hence, Wnt10b is a clastokine and a potential novel therapeutic target of postmenopausal osteoporosis and CKD-related bone disorder." (PMID 33013696, 2020). "For example, Wnt10b was recently identified as a clastokine, and a potential novel therapeutic target of postmenopausal osteoporosis." (PMID 33013696, 2020).
rheumatic diseases (1 paper, 2025). "The increased immunoexpression of Wnt‐10b in sensory neurons and β‐catenin in glial satellite cells in the TG of rats with TMJ arthritis further reinforces the involvement of the Wnt/β‐catenin pathway in the nociceptive mechanisms of rheumatic diseases." (PMID 41006957, 2025).